SHROOM1 (shroom family member 1)
Description:
May be involved in the assembly of microtubule arrays during cell elongation.
Synonyms: APXL2; KIAA1960
Tractability: PROTAC: ubiquitination databases record sites on it; its protein half-life has been measured.
Gene: Protein-coding gene on chromosome 5 (132,822,141 to 132,830,920, reverse strand). Ensembl gene ENSG00000164403.
Subcellular location: Cytoplasm, cytoskeleton
Subcellular location (Human Protein Atlas): Vesicles
Gene Ontology:
Molecular function: actin filament binding; myosin II binding
Biological process: actin filament bundle assembly; cell morphogenesis
Cellular component: adherens junction; apical junction complex; apical plasma membrane; cortical actin cytoskeleton; cytoskeleton
Genetic constraint (gnomAD): Loss-of-function variants: 53 observed, 53.09 expected, observed/expected ratio (o/e) 1, 90% interval 0.8 to 1.25. The upper end of that interval is the gene's LOEUF score, 1.25, which puts it in group 5 of 6, group 1 being the genes least tolerant of losing a copy. Missense variants: 1,179 observed, 1,022.6 expected, observed/expected ratio (o/e) 1.15, 90% interval 1.1 to 1.21. Synonymous variants: 490 observed, 438.66 expected, observed/expected ratio (o/e) 1.12, 90% interval 1.04 to 1.2.
Homologues: Orthologues: chimpanzee SHROOM1 (98% identical), macaque SHROOM1 (93% identical), pig SHROOM1 (74% identical), rat Shroom1 (61% identical), mouse Shroom1 (59% identical), dog SHROOM1 (58% identical), guinea pig SHROOM1 (53% identical), zebrafish shroom1 (25% identical), tropical clawed frog shroom1 (23% identical), Drosophila melanogaster Shrm (18% identical). Paralogues in human: SHROOM3 (28% identical), SHROOM2 (24% identical), SHROOM4 (17% identical).
Diseases named in the same sentence as SHROOM1 in open-access papers:
SHROOM1 is named in the same sentence as 13 diseases in open-access papers, as found by Europe PMC text mining. Sharing a sentence is not in itself a finding about the gene and the disease. The quoted sentences say what the papers report.
Arthritis (1 paper, 2018). Inflammation of a joint. "More importantly, we identified a set of genes with substantial differences in DNA methylation between very early RA and resolving arthritis, in particular SHROOM1." (PMID 29743579, 2018).
atrial septal defect 2 (1 paper, 2019). Any atrial heart septal defect in which the cause of the disease is a mutation in the GATA4 gene. "Diseases associated with SHROOM1 include atrial septal defect 2 and atrial heart septal defect." (PMID 31801612, 2019).
colorectal cancer (1 paper, 2020). A primary or metastatic malignant neoplasm that affects the colon or rectum. "In human colorectal cancer cell line HCT116, the efficiency of SHROOM1 knockdown was higher than in the control when a ds donor was used at the FBL or LMNA locus." (PMID 32823670, 2020).
Graves disease (1 paper, 2025). Graves' disease is an autoimmune disorder that leads to overactivity of the thyroid gland (hyperthyroidism).It is caused by an abnormal immune system response that causes the thyroid gland to produce too much thyroid hormones. "XIST, PPP1R2C, CALHM6, AL672277.1, TSIX, SHROOM1, ADTRP, JUND, SGK1, CHKA, AO008569.1, MAP7D2, and AIF1 were down-expressed genes in TS compared with both the healthy female and the female patient with Graves’ disease." (PMID 39851522, 2025).
heart defects (1 paper, 2019). "Therefore, hypermethylation of SHROOM1 in DS may be potentially associated with the pathophysiology of the congenital heart defects and osteoarthritis related to DS." (PMID 31801612, 2019). "In another study, hypermethylation of SHROOM1 was present in DS fetuses with or without congenital heart defects, as well as in fetuses with heart malformations." (PMID 31801612, 2019).
hepatoma (1 paper, 2020). "The same elevation of HDR efficiency was observed at the Actb locus in mouse hepatoma cell line Hepa1-6 with different types of donors when SHROOM1 was inhibited." (PMID 32823670, 2020).
knee osteoarthritis (1 paper, 2019). "It was recently reported that patients with knee osteoarthritis had marked hypermethylation status in all SHROOM1 differentially methylated sites between damaged and non-damaged tissues." (PMID 31801612, 2019).
osteoarthritis (1 paper, 2019). A noninflammatory degenerative joint disease occurring chiefly in older persons, characterized by degeneration of the articular cartilage, hypertrophy of bone at the margins and changes in the synovial membrane. "The authors suggested hypermethylated SHROOM1 as a promising candidate for functional studies of osteoarthritis pathology." (PMID 31801612, 2019).
cancer (3 papers, 2022 to 2025). A tumor composed of atypical neoplastic, often pleomorphic cells that invade other tissues. "SHROOM1 has been identified as a somatic hotspot mutation in major cancers, including LUAD." (PMID 40722386, 2025). "The eight cross-cancer CpGs were annotated to genes involved in transport (KCNA3, KCNAB3 and TRAPPC1), signal transduction (AGAP3 and LIME1), microtubule assembly (FES and SHROOM1), and metal binding (FURIN and AGAP3)." (PMID 35710732, 2022).
SHROOM1 also shares sentences with these, for which no sentence is quoted: gestational diabetes (1 paper); heart malformations (1); lung carcinoma (1); Turner syndrome (1).